STAT3 (signal transducer and activator of transcription 3)
Diseases named in the same sentence as STAT3 in open-access papers (continued):
Sharing a sentence is not in itself a finding about the gene and the disease.
tumor (continued). "Furthermore, embelin, a derivative from Embelia ribes, is known to inhibit XIAP (X-linked inhibitor of apoptosis protein) and is able to impair tumor proliferation by interfering in IL-6/STAT3 signaling." (PMID 24901008, 2014). "Recent studies have revealed STAT3 as a major player in the regulation of innate and adaptive tumor immunity and as a therapeutic target to enhance immune recognition and to break T cell tolerance of tumor cells." (PMID 24662939, 2014). "How are these findings related to the observation that STAT3 can function as a tumor suppressor?" (PMID 24995504, 2014). "However, the polarization of macrophages to the M2 phenotype disturbs this homeostasis and keeps STAT3 activated; this, in turn, attenuates anti-tumour immune responses." (PMID 24708807, 2014). "Next we examined the relevance of STAT3 signaling for IDO1 expression in human tumor tissue." (PMID 24657910, 2014). "STAT3 has been elegantly shown to promote tumor evasion of the immune system." (PMID 24743777, 2014). "It is important to note that much of the evidence supporting STAT3’s role as a potential tumor suppressor has been obtained through in vitro cell line experiments, which may limit its relevance for clinical GBM pathogenesis." (PMID 24518612, 2014). "In cancer, other molecules that may influence tumor growth by regulating the IL-6/STAT3 signaling pathway have been reported." (PMID 24901008, 2014). "Additionally, we assessed the effects of STAT3 inhibition on tumor angiogenesis using murine xenograft models." (PMID 24404126, 2014). "Through the activation of STAT-3 and in turn nuclear factor kappa B (NF-κB) signaling in inflammatory cells, these cytokines generate a positive feedback loop between tumor stem cells and immune cells, thus promoting cancer stem cells self-renewal and tumor growth." (PMID 24762066, 2014). "Although the role of STAT5 in skeletal muscle wasting is unknown, STAT3 binds to an analogous motif and was recently shown to mediate muscle atrophy in C26 tumor-bearing mice." (PMID 25539728, 2014). "PTEN is a critical tumor suppressor gene that negatively regulates STAT3 activity." (PMID 25539644, 2014). "Therefore WP1066 inhibition of STAT3 activity and tumour progression was due in part to reduced polymophonuclear infiltration and reduced STAT3-dependent transcription of pro-inflammatory IL-6, IL-11, IL-1α, IL-1β and COX2 genes." (PMID 24804649, 2014). "Moreover, caffeic acid, another major compound of the M. officinalis extract, was reported to effectively suppress pathological angiogenesis in tumor through inhibiting the activity of STAT3-HIF1α." (PMID 25314292, 2014). "New STAT3 inhibitors also can inhibit tumor proliferation, chemo-therapy resistance and metastasis." (PMID 25344679, 2014). "However, despite the overwhelming amount of information that supports STAT3 as an oncogene, there is some evidence that STAT3 can also suppress tumor growth." (PMID 24743777, 2014). "We hypothesized that residual cancer cells in the post-surgery setting may respond to inflammatory stimuli, enriching for tumor-initiating cells via STAT3 signaling." (PMID 25026286, 2014). "This study suggested STAT3 regulation of iNOS supported growth of malignant tumor cells." (PMID 24743777, 2014). "Moreover, a recent study detected increased nuclear-localization of Tyr705 phosphorylated STAT3 in about 57% (63 of 110) human primary PTC cases, preferentially in association with the tumor stroma." (PMID 24662939, 2014). "Because oncogenic stress can elicit growth inhibitory responses as an innate tumor defense mechanism, STAT3 signaling may also be networked with a similar tumor defense mechanism, which is activated in the face of aberrant STAT3 activation." (PMID 24662939, 2014). "To figure out whether this in vitro expression was maintained during in vivo proliferation of tumor cells, we evaluated the expression of activated forms of STAT3 in in vivo orthotopic tumors." (PMID 25359779, 2014).
tumor (continued). "The SIAH2-dependent proteasomal degradation of TYK2 we report here might represent a possibility to reduce aberrant STAT3 signaling and tumor progression." (PMID 24833526, 2014). "To test this hypothesis, we evaluated local recurrence after surgery, as read out of tumor initiating ability, in control- and STAT3-silenced BC cells." (PMID 25026286, 2014). "Indeed, studies including ours have demonstrated that STAT3 can mediate tumor suppressive signal transduction in different tumor types." (PMID 24662939, 2014). "For the first time, we demonstrate that while the tumor volumes are kept small as a result of paclitaxel treatment, populations of tumor cells within the residual tumors retain the activated JAK2/STAT3 pathway and are enriched in markers such as Oct4 and CD117." (PMID 24782986, 2014). "An earlier study demonstrated that IL6 is accountable for a higher incident rate of HCC in males than in females in a mouse model, suggesting that higher IL6 expression and the subsequent activation of STAT3 in surrounding liver “prime” events for tumor development." (PMID 25536056, 2014). "Furthermore, the authors found that STAT3 mediates the tumor suppressor effects by binding to GSK3β, which in turn promotes the phosphorylation and the degradation of Snail, a critical regulator of the EMT and cancer metastasis." (PMID 24995504, 2014). "Constitutive STAT3 activation contributes to proliferation and oncogenesis by modulating the expression of a variety of genes required for tumor cell survival, proliferation, and angiogenesis, as well as invasion and metastasis and commonly suggests poor prognosis." (PMID 25296162, 2014). "Other roles are discussed in the section below on the dual roles of STAT3 in tumor growth." (PMID 24743777, 2014). "IDO was expressed and STAT3 was acetylated in all tumor samples examined." (PMID 24657910, 2014). "STAT3 phosphorylation plays a crucial role in proliferation and survival of tumor cells." (PMID 24655440, 2014). "Moreover, it is well known that, particularly in the inflammatory setting, the activation of cytokine receptors/JAK/STAT3-axis plays a primary role in the crosstalk between tumor stroma and cancer cells, eventually driving tumor progression." (PMID 25026286, 2014). "In tumor-bearing state, G-CSF/IL-6 could endow neutrophils with protumor potential by inducing the enhanced activation of STAT3 and attenuating the activation of PI3K and p38 MAPK pathways in response to T-sMs." (PMID 25587026, 2014). "While STAT3 activation is clearly implicated in GBM survival through invasion, differentiation, angiogenesis, and immunosuppression, recent studies in GBM and other tumors have suggested a role for STAT3 in tumor suppression." (PMID 24518612, 2014). "Necdin expression is suppressed by STAT3 whose activation promotes tumor development." (PMID 25012566, 2014). "Stat3 phosphorylation was also up-regulated in fs188 tumours in vivo." (PMID 25119572, 2014). "Whether STAT3 is involved in mediating the positive effect of PKR in promoting tumor cell growth was then investigated." (PMID 25360179, 2014). "STAT3 was persistently activated in tumor-infiltrating B cells during tumor growth." (PMID 24782982, 2014). "Given that SOCS-3 is a negative regulator of STAT-3 activation, it was initially believed that it might function as a tumor suppressor and, hence, its expression might be repressed in neoplasms, particularly those with constitutive activation of STAT-3." (PMID 24593195, 2014). "Cancer cells and some of their surrounding inflammatory cells have been shown to produce and release various soluble factors (notably cytokines) into the tumor microenvironment, such that STAT3 in the cancer cell population is activated excessively and continuously." (PMID 24995504, 2014). "Phospho-STAT3 (pSTAT3) expressed in tumor cells was inhibited by sunitinib treatment." (PMID 25333973, 2014).
tumor (continued). "The diversity of signaling pathways in PCa tumor cells in which STAT3 acts as a major signaling node translates into it being a driving force in not only tumor proliferation and survival, but also in determining cell phenotype, behavior and interaction with stromal cells and the immune system." (PMID 24722453, 2014). "The STAT3 decoy oligonucleotide also inhibited tumor angiogenesis in murine tumor xenografts." (PMID 24404126, 2014). "In PCa, STAT3 activation associated with decreased AR expression is mediated through increased production of IL-6 and treating mice with soluble IL-6 receptor fusion protein significantly reduces CSC number and xenograft tumor growth." (PMID 24722453, 2014). "In many tumor types, STAT3 is constitutively activated and deregulated STAT3 signaling may contribute to the process of tumorigenesis." (PMID 25514788, 2014). "STAT3 is a critical mediator of differentiation, activation, migration and inflammatory capacity of immune cells and stromal cells that create the microenvironment supporting tumor cell growth." (PMID 24722453, 2014). "However, as has been the case with STAT1 some years earlier, a potentially tumor-suppressive role for STAT3 has also been recently proposed." (PMID 25268165, 2014). "STAT3 activation might be involved in tumor progression by modulation of the expression of factors related with cancer such as MMP9." (PMID 25359779, 2014). "Thus, STAT3 has a very direct role in suppressing tumor immune surveillance and function by regulation of these cytokines." (PMID 24743777, 2014). "Nevertheless, the effect of Ras/Raf activation on STAT3 was consistent in these two tumor types in that, in both MTC and PTC, Ras/Raf activates STAT3 via the IL-6 family cytokine-mediated gp130/JAK pathway and STAT3 operates in the context of tumor suppression." (PMID 24662939, 2014). "In addition, studies also indicated that activated Stat3 can promote tumor cell migration and invasion and suppressed tumor-immune surveillance." (PMID 24416452, 2014). "Moreover, targeting STAT3 transcriptional activity using parthenolide, induces cell death in tumor initiating cells isolated from a number of PCa cell lines and prevents their growth in vivo." (PMID 24722453, 2014). "Indeed, despite the fact that endothelial cells secrete many cytokines and growth factors, silencing of IL-6 with shRNA (or use of a netutralizing antibody) completely abrogated induced phosphorylation of STAT3 in tumor cells." (PMID 24533454, 2014). "Furthermore, astaxanthin downregulated the expression of STAT-3 target genes involved in cell proliferation, invasion and angiogenesis, and reduced microvascular density, thereby preventing tumour progression." (PMID 25296162, 2014). "We next sought to examine whether the decrease in the microvessel density (seen in the previous experiment) was due to a direct effect of the STAT3 decoy oligonucleotide on the endothelial cell or a result of a decrease in tumor cell production of VEGF." (PMID 24404126, 2014). "In understanding the functional effect of these results, a study showed that inhibition of STAT3 was responsible for NSCLC tumor growth suppression suggesting that inhibition of JAK2-STAT3 could be a mechanism for cellular apoptosis in P7170 treated cells." (PMID 25466244, 2014). "Numerous studies have shown that STAT3 inhibitors have tumor suppressive effects on various tumors." (PMID 25344679, 2014). "Thus far, STAT3 has been shown to directly affect both of these mechanisms by upregulating anti-apoptosis proteins as well as cyclin D1 giving substantial reason to those targeting STAT3 for suppressing tumor growth." (PMID 24743777, 2014). "In addition to upregulating numerous genes involved in proliferation, survival, invasion and metastasis of tumor cells, STAT3 induces the expression of many cytokines, such as IL-6, IL-10, TGF-β and VEGF, that are associated with cancer-promoting inflammation." (PMID 25149535, 2014).
tumor (continued). "In addition, STAT3 can regulate other transcription factors that also support tumor growth, thus STAT3 can also indirectly support tumor growth by promoting survival, angiogenesis, metastasis, and even pluripotency." (PMID 24743777, 2014). "In addition to regulating proliferation and apoptosis, transcriptional products of STAT3 facilitate the establishment of an immune-suppressed microenvironment, thereby promoting tumor progression." (PMID 24806510, 2014). "Conversely, conditional deletion of STAT3 results in reduced tumor development in mice." (PMID 25126546, 2014). "STAT3 and NF-κB are reported as two major factors controlling the ability of preneoplastic as well as malignant cells to resist apoptosis-based tumor-surveillance and regulating tumor angiogenesis and invasiveness." (PMID 24757666, 2014). "Also, in cell lines of malignant fibrous histiocytoma, a high secretion of IL-6 and constitutive activation of STAT3 were reported, reflecting an increase of tumor cell proliferation." (PMID 24901008, 2014). "This may indicate biological differences in tumours where both STAT3 and β-catenin are activated compared to those where only one is activated." (PMID 25348333, 2014). "Notably, tumor cells expressing phosphorylated STAT3 localized primarily adjacent to blood vessels and correlated with expression of the proliferation marker Ki67." (PMID 24533454, 2014). "Dysregulation and constitutive activation of STAT3 stimulates cancer cell growth and contributes to tumor development and progression by upregulation of STAT3 target genes including Bcl-2, c-myc, cyclin D1 and VEGF, which can enhance cell survival, proliferation and promote angiogenesis." (PMID 24675768, 2014). "Moreover, this study revealed an inverse-correlation between tumor size and STAT3 activity, specifically in B-RafV600E-positive cases." (PMID 24662939, 2014). "Such discrepancies in study results may reflect the dependence of STAT3 tumorigenic versus tumor suppressor function on the tumor genetic background, potentially confounding the results." (PMID 24518612, 2014). "Conversely, blocking STAT3 activity in tumor cells induces production of the cell-extrinsic factors that enable dendritic cell maturation and function, leading to T cell activation and subsequent anti-tumor immune responses." (PMID 24662939, 2014). "While these studies support the tumor suppressive role of STAT3 in the context of MTC, a recent study showed that AZD1480, a small molecule inhibitor of JAK1/2, could also inhibit the growth of MTC cell lines." (PMID 24662939, 2014). "Our study reveals the novel molecular mechanism through which regorafenib triggers an SHP-1 tumor suppressive pathway to exert superior anti-tumor effects by promoting SHP-1 tyrosine phosphatase activity that targets the oncogenic expression of p-STAT3 Tyr 705 directly." (PMID 25071018, 2014). "Besides, STAT3 mediated pro-oncogenic inflammation has also been well documented to promote tumor initiation and progression." (PMID 24380387, 2013). "Furthermore, niclosamide completely blocked erlotinib-stimulated STAT3 phosphorylation in the tumor tissues." (PMID 24019973, 2013). "Furthermore, B cells with activated STAT3 are mainly found in or near tumor vasculature and correlate significantly with overall STAT3 activity in human tumors." (PMID 23734190, 2013). "In contrast, adding Stat3−/− B cells to the tumor environment reduced tumor growth." (PMID 23734190, 2013). "Previous studies have focused on the effects of STAT3 inhibition on the bulk tumor cell population." (PMID 24376586, 2013). "The production of pro-inflammatory cytokines, IL-1β, IL-6, and TNFα, all of which facilitate tumor growth, in the tumor microenvironment might be due to STAT3 hyperactivation in both the tumor and immune cells." (PMID 23730621, 2013).
tumor (continued). "Preclinical studies have shown that HNSCC cell lines stably transfected with a constitutively active STAT3 construct expressed elevated levels of STAT3 target genes, including Bcl-xL and cyclin D1, leading to increased proliferation in vitro and more rapid tumor growth rates in vivo." (PMID 23577258, 2013). "Moreover, a constitutive activation of Stat3 has been reported in a variety of tumor cells to depend upon c-Src and should protect cells from apoptosis." (PMID 23825704, 2013). "We next evaluated in human tumor tissues whether our findings in mouse tumor models that B cells with elevated Stat3 activity are crucial for tumor progression in part via promoting tumor angiogenesis are clinically relevant." (PMID 23734190, 2013). "Stat3 plays an important role in the process in tumor immunosuppression." (PMID 23937717, 2013). "In addition, targeting Stat3 increases tumor cell apoptosis and decreased Bcl-xL expression in a head and neck xenograft model." (PMID 23577258, 2013). "Moreover, the first-line targeted drug sunitinib has recently been shown to elicit its anti-tumor activity by STAT3 inhibition." (PMID 23690956, 2013). "We show that upon co-culturing APC with various primary and tumor cell lines STAT3 phosphorylation and IL-10 expression are induced, and such regulation could be suppressed by specific CD47 siRNAs and shRNAs." (PMID 24073274, 2013). "Moreover, STAT3 activation in tumor microenvironment also reduces the activity of NK cells, thereby protecting tumor cells during circulation." (PMID 24199193, 2013). "Apart from dendritic cells, other immune effector cells such as macrophages, neutrophils, natural killer cells, and regulatory T cells, in response to the growth factors released by tumor cells, show constitutive activation of STAT3, thus limiting their own ability of immune surveillance." (PMID 24199193, 2013). "Thus, expression of a constitutively active form of Stat3 significantly increased the rate of tumor progression in this model system." (PMID 23577258, 2013). "Whether STAT3 in B cells synergistically work with other immune cells including myeloid cells and T cells for tumor angiogeniesis warrants further investigation." (PMID 23734190, 2013). "Notably, we showed that HMGA1 induces STAT3 expression in lymphoid tumorigenesis, and STAT3 inhibitors are cytotoxic to the HMGA1-driven tumor cells." (PMID 23658826, 2013). "Stat3 was activated in lung epithelial cells of both systemic inflammation-induced tumor models." (PMID 23613996, 2013). "Using antibody specific for phosphorylated STAT3 (p-STAT3), activated STAT3 could be demonstrated as brown nuclei stain in the tumor cells." (PMID 24380387, 2013). "This indicates other mechanisms may activate STAT3, including other cell types within the tumor microenvironment." (PMID 24244348, 2013). "Moreover, real-time RT-PCR showed that Stat3 activity promoted expression of these pro-angiogenic genes in B cells isolated from tumor tissues and the tumor draining lymph nodes." (PMID 23734190, 2013). "Furthermore, pharmacological inhibition of both NF-κB and STAT3 is necessary in order to prolong survival and decrease tumor burden in vivo." (PMID 24244348, 2013). "By that means STAT3-mediated acetylation affects NF-κB activity - a mechanism, which plays a role in cancer – as it is often the result of chronic stimulation with cytokines in a tumor microenvironment." (PMID 23915189, 2013). "Therefore, in this study, we introduced a STAT3 activator, IL-22, that exhibits a tumor enhancement mechanism similar to IL-6." (PMID 23379788, 2013). "However, compelling evidence suggests that STAT3 is constitutively activated in many cancers and plays a pivotal role in tumor growth and metastasis." (PMID 24199193, 2013). "Moreover, the density of B cells in human tumor tissues correlates significantly with expression levels of several STAT3-downstream pro-angiogenic genes, as well as the degree of tumor angiogenesis." (PMID 23734190, 2013).